RNU6-614P (RNA, U6 small nuclear 614, pseudogene)
Gene: Small nuclear RNA gene on chromosome 21 (13,047,583 to 13,047,689, forward strand). Ensembl gene ENSG00000207097.
Homologues: Orthologues: chimpanzee U6 (100% identical), macaque U6 (90% identical), dog U6 (64% identical), rabbit U6 (63% identical), pig U6 (60% identical), rabbit U6 (60% identical). Paralogues in human: U6 (99% identical), RNU6-1132P (98% identical), RNU6-1293P (96% identical), RNU6-156P (96% identical), RNU6-721P (96% identical), RNU6-458P (95% identical), U6 (95% identical), RNU6-1207P (91% identical), RNU6-811P (91% identical), RNU6-978P (91% identical), RNU6-452P (86% identical), RNU6-666P (85% identical), and 1289 more.